SLC35B1 (solute carrier family 35 member B1)
Description:
ATP:ADP antiporter that catalyzes the exchange of ATP and ADP across the endoplasmic reticulum (ER) membrane. Imports ATP from the cytosol to the ER lumen and exports ADP in the opposite direction. Regulates ER energy metabolism and protein biogenesis. Appears to be part of a calcium-dependent ER to cytosol low energy response axis, where calcium efflux from ER to the cytosol triggers ATP import into the ER lumen to maintain sufficient ATP supply. Provides ATP to ER chaperone HSPA5 that drives protein folding and trafficking in the ER. Can transport dATP, UTP or UDP in exchange for ATP, but the physiological relevance of this process remains to be established. [Isoform 1]: ATP:ADP antiporter. [Isoform 2]: ATP:ADP antiporter.
Synonyms: AXER; UGTrel1
Tractability: Antibody: UniProt predicts a signal peptide or a membrane-spanning region. PROTAC: its protein half-life has been measured.
Gene: Protein-coding gene on chromosome 17 (49,700,934 to 49,709,014, reverse strand). Ensembl gene ENSG00000121073.
Subcellular location: Endoplasmic reticulum membrane
Subcellular location (Human Protein Atlas): Endoplasmic reticulum; Vesicles
Gene Ontology:
Molecular function: ATP:ADP antiporter activity; protein binding; UDP-galactose transmembrane transporter activity
Biological process: UDP-galactose transmembrane transport; ADP transport; ATP transport; transmembrane transport
Cellular component: endoplasmic reticulum; endoplasmic reticulum membrane; intracellular membrane-bounded organelle
Genetic constraint (gnomAD): Loss-of-function variants: 21 observed, 32.64 expected, observed/expected ratio (o/e) 0.64, 90% interval 0.46 to 0.93. The upper end of that interval is the gene's LOEUF score, 0.93, which puts it in group 3 of 6, group 1 being the genes least tolerant of losing a copy. Missense variants: 299 observed, 371.56 expected, observed/expected ratio (o/e) 0.8, 90% interval 0.73 to 0.89. Synonymous variants: 154 observed, 150.34 expected, observed/expected ratio (o/e) 1.02, 90% interval 0.9 to 1.17.
Homologues: Orthologues: chimpanzee SLC35B1 (100% identical), dog SLC35B1 (98% identical), pig SLC35B1 (98% identical), guinea pig SLC35B1 (97% identical), rat Slc35b1 (96% identical), mouse Slc35b1 (96% identical), rabbit SLC35B1 (92% identical), tropical clawed frog slc35b1 (81% identical), zebrafish slc35b1 (73% identical), Drosophila melanogaster meigo (51% identical), Caenorhabditis elegans hut-1 (45% identical). Paralogues in human: SLC35B2 (32% identical), SLC35B3 (28% identical), SLC35B4 (19% identical).
Diseases named in the same sentence as SLC35B1 in open-access papers:
SLC35B1 is named in the same sentence as 9 diseases in open-access papers, as found by Europe PMC text mining. Sharing a sentence is not in itself a finding about the gene and the disease. The quoted sentences say what the papers report.
mastitis (1 paper, 2024). Inflammation of breast tissue during lactation or postpartum due to an obstructed duct or infection. "Similarly, the expression of genes related to lactation and other mammary traits (SLC38A2, SLC35B1), fertility (SLC38A2, MT1E), susceptibility to paratuberculosis, mastitis and trypanosomiasis (IL6), and feed intake/efficiency (MT1E, SLC38A2) was upregulated in Mirandesa cattle." (PMID 39333243, 2024).
kidney disease (1 paper, 2025). "In silico perturbation of the disease cells by altering gene expressions revealed that deleting the gene Slc35b1, abundantly expressed in cells of UMOD kidney disease, had the greatest impact in moving the disease cell status closer to normal kidney cells." (PMID 40106407, 2025).
SLC35B1 also shares sentences with these, for which no sentence is quoted: cancer (2 papers); breast carcinoma (1); cardiac arrest (1); heart failure (1); Obesity (1); ovarian carcinoma (1); trypanosomiasis (1).